PLD4 (phospholipase D family member 4)
Description:
Lysosomal 5'->3' exonuclease that functions in nucleic-acid sensing by immune cells. Hydrolyzes phosphodiester bond in single-stranded RNA and DNA molecules, with a higher efficiency for molecules with 5' uridine and guanosine residues. It can stall at certain sites and does not necessarily proceed to complete exonucleolytic degradation, thereby producing nucleoside 3'-monophosphates but also 5'-end 5'-hydroxy deoxyribonucleotide/ribonucleotide fragments. Through the processing of self and exogenous RNA and DNA molecules, provides molecular signals to toll-like receptors (TLRs) in innate immunity. Partially redundant with PLD3, it cooperates with the RNase T2/RNASET2 to generate 2',3'-cGMP and cytidine-rich RNA fragments that occupy the two TLR7 ligand-binding pockets, to trigger receptor activation and signaling. Can exert polynucleotide phosphatase activity toward 5'-phosphorylated single-stranded DNA substrates although at a slow rate. Could play a role in phagocytosis of activated microglia (By similarity). Can alternatively catalyze the transfer (transphosphatidylation) of a glycerol group between (S,R)- lysophosphatidylglycerol (LPG) and monoacylglycerol (MAG). The reaction is characterized by an R-to-S stereo-inversion which is essential for the resistance of the produced (S,S)-bis(monoacylglycero)phosphates (BMPs) to lysosomal degradation. The resulting BMPs, are phospholipids required for the formation of lysosomal intralumenal vesicles (ILVs) where lipid degradation can occur.
Synonyms: C14orf175; SLEB18
Tractability: Small molecule: a high-quality ligand is known. Antibody: UniProt predicts a signal peptide or a membrane-spanning region. PROTAC: ubiquitination databases record sites on it; its protein half-life has been measured.
Target class: Enzyme; Hydrolase
Gene: Protein-coding gene on chromosome 14 (104,924,713 to 104,937,761, forward strand). Ensembl gene ENSG00000166428.
Subcellular location: Lysosome; Endoplasmic reticulum membrane; Golgi apparatus, trans-Golgi network membrane; Nucleus; Early endosome; Cytoplasmic vesicle, phagosome
Pathways (Reactome):
Metabolism: Synthesis of IP3 and IP4 in the cytosol; Synthesis of PG
Immune System: Role of phospholipids in phagocytosis
Gene Ontology:
Molecular function: 5'-3' DNA exonuclease activity; 5'-3' RNA exonuclease activity; acyltransferase activity, transferring groups other than amino-acyl groups; catalytic activity
Biological process: innate immune response; phagocytosis; positive regulation of intralumenal vesicle formation; negative regulation of toll-like receptor 9 signaling pathway
Cellular component: lysosome; early endosome; endomembrane system; endoplasmic reticulum membrane; nucleus; phagocytic vesicle; trans-Golgi network membrane; cytoplasm; endoplasmic reticulum; Golgi apparatus
Genetic constraint (gnomAD): Loss-of-function variants: 58 observed, 45.59 expected, observed/expected ratio (o/e) 1.27, 90% interval 1.03 to 1.58. The upper end of that interval is the gene's LOEUF score, 1.58, which puts it in group 6 of 6, group 1 being the genes least tolerant of losing a copy. Missense variants: 698 observed, 580.6 expected, observed/expected ratio (o/e) 1.2, 90% interval 1.13 to 1.28. Synonymous variants: 252 observed, 243.25 expected, observed/expected ratio (o/e) 1.04, 90% interval 0.93 to 1.15.
Gene-disease validity (ClinGen):
ClinGen rates the evidence that PLD4 causes each of these diseases.
systemic lupus erythematosus 18 (autosomal recessive): Moderate. Any systemic lupus erythematosus in which the cause of the disease is a variation in the PLD4 gene.
Homologues: Orthologues: chimpanzee PLD4 (99% identical), macaque PLD4 (94% identical), pig PLD4 (81% identical), dog PLD4 (77% identical), rat Pld4 (75% identical), guinea pig PLD4 (74% identical), mouse Pld4 (74% identical), Drosophila melanogaster Pld3 (34% identical), Drosophila melanogaster CG43345 (33% identical), Caenorhabditis elegans T05C3.6 (31% identical), Caenorhabditis elegans F09G2.8 (30% identical), Caenorhabditis elegans Y51A2D.13 (27% identical), and 1 more. Paralogues in human: PLD3 (41% identical), PLD5 (30% identical).
Diseases named in the same sentence as PLD4 in open-access papers:
PLD4 is named in the same sentence as 30 diseases in open-access papers, as found by Europe PMC text mining. Sharing a sentence is not in itself a finding about the gene and the disease. The quoted sentences say what the papers report.
systemic lupus erythematosus (9 papers, 2017 to 2025). An autoimmune multi-organ disease typically associated with vasculopathy and autoantibody production. "Genetic studies have linked single nucleotide polymorphisms (SNPs) in PLD4 to the onset of rheumatoid arthritis, systemic lupus erythematosus (SLE), and systemic sclerosis." (PMID 40811510, 2025). "PLD4 loss-of-function mutations in patients with systemic lupus erythematosus leads to excessive activation of TLR7 and TLR9." (PMID 40931063, 2025). "Human polymorphisms in the PLD4 gene have been linked by genome-wide association studies to systemic sclerosis, rheumatoid arthritis, and systemic lupus erythematosus." (PMID 37555846, 2023). "Nonetheless, genome-wide association studies show PLD4 is strikingly associated with human systemic lupus erythematosus and dsDNA Abs diagnostic of lupus." (PMID 37555846, 2023). "A major distinction between PLD4-deficient mice on the BALB/c background compared with B6 is the development of lupus-like features and B cell hyperreactivity." (PMID 37555846, 2023). "This is considered significant, because human genome-wide association studies have linked PLD4 polymorphisms to systemic sclerosis, lupus, and rheumatoid arthritis." (PMID 37555846, 2023). "In this line, genetic variants in PLD4 have been recently linked to systemic lupus erythematosus in human patients by GWAS." (PMID 33288674, 2021). "PLD4, a lupus risk allele and the most highly up-regulated gene in IgMhi compared with IgMlo TS B cells, is up-regulated along the developmental pathway to MZBs and limits responses to CpG." (PMID 33538776, 2021). "Recently, PLD4 was shown to be associated with RA, systemic lupus erythematosus, and systemic sclerosis, suggesting a role of PLD4 in autoimmune diseases." (PMID 32370217, 2020). "In any case, our findings imply that human PLD4 polymorphism and deficiency may have diverse phenotypic presentations ranging from hemophagocytic lymphohistiocytosis to lupus, and that all may be treatable by blockade of TLR9." (PMID 37555846, 2023). "Interestingly, very recently, PLD4 was genetically linked to systemic lupus erythematosus in human patients in a genome-wide association study, and Pld4 mutant mice exhibit an autoimmune phenotype, strengthening the role of PLD4 in innate immunity." (PMID 33288674, 2021). "Genome-wide association studies have shown that the PLD4 gene is linked to autoimmune diseases, such as systemic sclerosis, systemic lupus erythematosus (SLE), and rheumatoid arthritis." (PMID 35812450, 2022). "According to results of previous studies, PLD4 loci were reported to be associated with RA, and also associated with systemic lupus erythematosus (SLE) and systemic sclerosis (SSc)." (PMID 28969061, 2017). "The lupus risk allele and regulator of TLR9 responses PLD4 was the most highly differentially expressed gene in IgMhi TS B cells." (PMID 33538776, 2021). "Phospholipase D3 (PLD3) and phospholipase D4 (PLD4), the most recently described lysosomal nucleases, are associated with Alzheimer’s disease, spinocerebellar ataxia, and systemic lupus erythematosus." (PMID 33288674, 2021). "In this article, we compare a Pld4 null mutant identified on the BALB/c background, Pld4thss/thss, which has distinct phenotypes: short stature, thin hair, and features of systemic lupus erythematosus." (PMID 37555846, 2023).
colon cancer (6 papers, 2021 to 2025). "Phospholipase D4 (PLD4) has been shown to enhance the anti-tumor effects of M1 macrophages in colon cancer cells." (PMID 40034694, 2025). "Although not much data have been published on the role of PLD4 in cancer, PLD4 has been reported as a critical factor for tumor as it plays an important role in anti-tumor activities in colon cancer and renal fibrosis." (PMID 37165046, 2023). "Mechanistic studies showed that the expression of phospholipase D4 (PLD4) in TAMs promotes the activation of M1 macrophages, resulting in an antitumor effect on colon cancer cells." (PMID 36982677, 2023).
rheumatoid arthritis (6 papers, 2014 to 2025). A chronic, systemic autoimmune disorder characterized by inflammation in the synovial membranes and articular surfaces. "PLD4 encodes phospholipase D4, which is associated with various pathologies, including Alzheimer’s disease, rheumatoid arthritis, systemic sclerosis, and other autoimmune and autoinflammatory diseases." (PMID 41465472, 2025). "Recent studies revealed an association between variants in PLD4 and two autoimmune diseases in human, namely systemic sclerosis and rheumatoid arthritis, disorders with inflammatory skin lesions and interstitial lung diseases." (PMID 25052073, 2014). "PLD4 variants have been linked to autoimmune disease, particularly rheumatoid arthritis, but there is no such association with PLD3." (PMID 33830999, 2021).
systemic sclerosis (6 papers, 2014 to 2025). A chronic disorder, possibly autoimmune, marked by excessive production of collagen which results in hardening and thickening of body tissues. "Likewise, PLD4 is also of interests as it is an exonuclease with regulatory role in breaking down nucleic acids, and genome-wide genetic variants have been associated with SLE, systemic sclerosis and RA." (PMID 35799782, 2022).
autoimmune disease (5 papers, 2014 to 2025). A disorder resulting from loss of function or tissue destruction of an organ or multiple organs, arising from humoral or cellular immune responses of the individual to their own tissue constituents. "A recent report argued that both PLD3 and PLD4 have 5’ exonuclease activity and implicated this activity in the function of antigen presenting cells in the context of autoimmune diseases." (PMID 33830999, 2021). "Interestingly, despite their differing typical localizations—DNASE1L3 being extracellular and PLD4 intracellular—both DNASE1L3 and PLD4 are associated with human autoimmune diseases and display similar phenotypes in genetically modified mice." (PMID 40811510, 2025). "These evidences suggest a role of PLD4 in autoimmune diseases." (PMID 28969061, 2017).
nephritis (3 papers, 2023 to 2025). Inflammation of renal tissue. "Mice with a nonsense mutation in PLD4 develop SLE-like autoantibody production and nephritis in a TLR9-dependent manner, highlighting the critical role of PLD4 in maintaining immune tolerance across species." (PMID 40811510, 2025). "Among various organs accumulating autoimmune damage, inflammatory genes (Tnf, Cxcl10, Mx2 and Ifng) were most prominently elevated in the kidneys of Pld4−/− mice compared with in the wild-type and Pld4+/− mice, consistent with the nephritis manifestation in patients." (PMID 40931063, 2025). "Together, the manifestations observed in mice support the pivotal roles of PLD4 in the development of SLE and effect of inflammatory responses in nephritis pathogenesis." (PMID 40931063, 2025). "As regards clinical manifestations, the high PLD4 + blast group showed higher rates of complication of nephritis and higher titer of anti-Sm antibodies, but not anti-dsDNA antibodies than the low group." (PMID 37840148, 2023).
Zinc deficiency (3 papers, 2014 to 2025). A deficiency of the essential metal Zinc; an essential cofactor for many enzymes. "Moreover, a nonsense mutation in PLD4 and a splice variant in SLC39A4 are responsible for bovine hereditary zinc deficiency in Fleckvieh and Holstein cattle, respectively." (PMID 40240941, 2025). "Our results strongly support that a nonsense mutation (p.W215X) in the PLD4 encoding gene is causative for this disease in the Fleckvieh breed and that zinc deficiency is not involved in the aetiology of the disease." (PMID 25052073, 2014). "However, the PLD4 variant and the previously reported SLC39A4-associated zinc deficiency in Holstein cattle (BHZD) could be ruled out due to their clinical differences." (PMID 32448141, 2020).
lupus nephritis (2 papers, 2023 to 2025). Glomerulonephritis in the context of systemic lupus erythematosus. "Patients with PLD4 deficiency uniformly develop lupus nephritis, with scRNA-seq and CyTOF analyses suggesting that pDCs are the predominant cellular drivers of upregulated type I IFN and TLR signalling in the patient PBMCs." (PMID 40931063, 2025). "PLD4 + blasts were sorted from one patient having SLE flare with increased titers of anti-dsDNA (> 400 IU/mL), anti-Sm (46 IU/mL), and anti-SS-A (> 1200 IU/mL) antibodies and class IV lupus nephritis." (PMID 37840148, 2023).
pancreatic cancer (2 papers, 2023). "Although LIPE, MT2A, PLD4 and ZNF589 have been studied in other tumours, their relationship with tumour-associated macrophages in pancreatic cancer remains to be investigated." (PMID 37469705, 2023). "Furthermore, the IL-7R, PLD4, and ID3 markers were statistically significant both in the univariate and multivariate models for differentiating pancreatic cancer from non-pancreatic cancer." (PMID 37165046, 2023). "However, ABCB4, ENPP6, FGFBP2, MT2A, OXER1, PLD4 and ZNF589 were low expressed in pancreatic cancer tissues." (PMID 37469705, 2023).
Splenomegaly (2 papers, 2021 to 2025). Abnormal increased size of the spleen. "A previous study reported on the inflammatory phenotypes in PLD4-deficient mice, such as splenomegaly, and increased concentrations of IFN-γ and CXCL10 in plasma." (PMID 34737744, 2021).
anemia (1 paper, 2023). A reduction in the number of red blood cells, the amount of hemoglobin, and/or the volume of packed red blood cells. "The anemia, blood monocytosis, and splenic neutrophilia of Pld4thss/thss mice were also TLR9 dependent and shared with PLD4-deficient mice on the B6 background." (PMID 37555846, 2023).
Autoimmunity (1 paper, 2025). The occurrence of an immune reaction against the organism's own cells or tissues. "Pld4-deficient mice presented with autoimmunity and cell-intrinsic expansion of plasmacytoid dendritic cells and plasma cells." (PMID 40931063, 2025).
fibrosis (1 paper, 2023). the formation of excess fibrous connective tissue in an organ or tissue in a reparative or reactive process. "Previous research has found that the expression of PLD4 is upregulated in mice and human kidneys after fibrosis." (PMID 36866272, 2023).
gastric cancer (1 paper, 2021). A primary or metastatic malignant neoplasm involving the stomach. "In addition, APBB1IP is a signature gene that contributes to clinical gastric cancer (GC) diagnosis and early detection, and the PLD4 and PLD3 enzymes strongly affect inflammatory cytokine production via the degradation of nucleic acids, thus serving as important regulators of inflammatory disease." (PMID 34916564, 2021).
parasitemia (1 paper, 2022). "NR1D1, NDRG2, and PLD4 showed significant negative correlations with parasitemia, suggesting that downregulation of transcription could be driven by high parasite burden and/or the concomitant inflammation associated with symptomatic infection." (PMID 35475529, 2022).
seminoma (1 paper, 2025). A radiosensitive malignant germ cell tumor found in the testis (especially undescended), and extragonadal sites (anterior mediastinum and pineal gland). "Among these, SLC5A5 and SPTBN4 emerged as risk factors for seminoma, whereas PLD4 was identified as a protective factor." (PMID 40321316, 2025).
Sepsis (1 paper, 2023). Sepsis is defined as life-threatening organ dysfunction caused by a dysregulated host response to infection. "In this study, the key genes downregulated during sepsis also encoded proteins responsible for the immune response, including the expression of antigen-presenting cells, the regulation of cytokine production, and the activation of B and T lymphocytes (i.e., CD79A, HLA-DQB2, PLD4, and CCR7)." (PMID 37298316, 2023). "In addition, we identified key genes that were upregulated in sepsis, namely, S100A8, S100A9, and CR1, as well as those that were downregulated, namely, CD79A, HLA-DQB2, PLD4, and CCR7." (PMID 37298316, 2023).
tumor (6 papers, 2023 to 2025). "We also examined the distribution of each gene in the 5-gene signature in GGO cells and discovered PLD4, NT5E and MAOB were differentially expressed between cancer cells and non-tumor cells, suggesting a more critical physiological significance." (PMID 38434969, 2024). "Few studies have investigated the role of PLD4 and ID3 in tumor growth and inhibition, especially PDAC." (PMID 37165046, 2023). "However, the potential roles of PLD4 in tumor progression is still largely unknown." (PMID 36866272, 2023). "Although we found that IL-7R, PLD4, and ID3 are differently expressed in human PBMC of PDAC patients, the functional role of marker-expressing immune cells, spatiotemporal relationship of the markers in tumor development, and precise mechanisms for marker upregulation remain unclear." (PMID 37165046, 2023). "However, we found that PLD4 levels were downregulated in PDAC and well correlated with tumor stage (data not shown)." (PMID 37165046, 2023).
cancer (3 papers, 2021 to 2024). A tumor composed of atypical neoplastic, often pleomorphic cells that invade other tissues. "Cancer development and progression was seen to be affected by Tnfrsf1a, Adrbk2, Pld4, Gnat1 and Samsn1 in other studies." (PMID 34185104, 2021).
infection (2 papers, 2022 to 2025). The state of being infected such as from the introduction of a foreign agent such as serum, vaccine, antigenic substance or organism. "In addition, enzymes related to PA synthesis, including phospholipase D family member 3 (Pld3), Pld4, Dgki, Dgkk, and Dgkg, were upregulated after infection." (PMID 40463366, 2025).
inflammation (1 paper, 2024). Aberrant reaction of the microcirculation characterized by movement of fluid and leukocytes from the blood into extravascular tissues. "Pld4-deficient mice have inflammatory disease and an exaggerated TLR9 response, while Pld4- and Pld3-knockdown mice die before the age of 21 days due to lethal liver inflammation." (PMID 37979047, 2024).
PLD4 also shares sentences with these, for which no sentence is quoted: Alzheimer disease (2 papers); hemophagocytic lymphohistiocytosis (1); interstitial lung disease (1); macrophage activation syndrome (1); multiple sclerosis (1); psychosis (1); renal fibrosis (1); spinocerebellar ataxia (1); triple-negative breast carcinoma (1).